HASPIN (histone H3 associated protein kinase)
Description:
Serine/threonine-protein kinase that phosphorylates histone H3 at 'Thr-3' (H3T3ph) during mitosis. May act through H3T3ph to both position and modulate activation of AURKB and other components of the chromosomal passenger complex (CPC) at centromeres to ensure proper chromatid cohesion, metaphase alignment and normal progression through the cell cycle.
Synonyms: GSG2
Tractability: Small molecule: a structure with a bound ligand is known; a high-quality ligand is known; it has a high-quality binding pocket; it belongs to a druggable protein family. PROTAC: it is named in the literature on targeted protein degradation; ubiquitination databases record sites on it; a small molecule that binds it is known.
Target class: Kinase; Enzyme; Other protein kinase Haspin family; Other protein kinase group; Protein Kinase
Gene: Protein-coding gene on chromosome 17 (3,723,903 to 3,726,699, forward strand). Ensembl gene ENSG00000177602.
Subcellular location: Nucleus; Chromosome; Cytoplasm, cytoskeleton, spindle
Subcellular location (Human Protein Atlas): Nucleoplasm
Gene Ontology:
Molecular function: ATP binding; histone H3T3 kinase activity; protein binding; protein kinase activity; protein serine kinase activity; histone kinase activity; protein serine/threonine kinase activity
Biological process: intracellular signal transduction; mitotic sister chromatid cohesion; mitotic spindle assembly checkpoint signaling; protein localization to chromosome, centromeric region; protein phosphorylation; chromatin remodeling; chromosome organization; negative regulation of mitotic cell cycle phase transition
Cellular component: centrosome; chromosome; nucleoplasm; nucleus; spindle
Genetic constraint (gnomAD): Loss-of-function variants: 27 observed, 34.9 expected, observed/expected ratio (o/e) 0.77, 90% interval 0.57 to 1.07. The upper end of that interval is the gene's LOEUF score, 1.07, which puts it in group 4 of 6, group 1 being the genes least tolerant of losing a copy. Missense variants: 1,016 observed, 1,025.1 expected, observed/expected ratio (o/e) 0.99, 90% interval 0.94 to 1.04. Synonymous variants: 440 observed, 409.66 expected, observed/expected ratio (o/e) 1.07, 90% interval 0.99 to 1.16.
Homologues: Orthologues: chimpanzee HASPIN (99% identical), macaque HASPIN (92% identical), dog HASPIN (73% identical), pig HASPIN (71% identical), guinea pig HASPIN (65% identical), rabbit HASPIN (64% identical), rat Haspin (62% identical), mouse Haspin (62% identical), tropical clawed frog haspin (36% identical), zebrafish haspin (33% identical), Caenorhabditis elegans hasp-1 (23% identical), Drosophila melanogaster Haspin (21% identical), and 4 more. Paralogues in human: IRAK1 (11% identical), IRAK2 (10% identical), IRAK4 (10% identical), IRAK3 (8% identical).